PID1 (phosphotyrosine interaction domain containing 1)
Diseases named in the same sentence as PID1 in open-access papers:
PID1 is named in the same sentence as 38 diseases in open-access papers, as found by Europe PMC text mining. Sharing a sentence is not in itself a finding about the gene and the disease. The quoted sentences say what the papers report.
glioma (10 papers, 2016 to 2025). A benign or malignant brain and spinal cord tumor that arises from glial cells (astrocytes, oligodendrocytes, ependymal cells). "The small number of articles reporting on PID1 to date hardly clarifies the role of PID1 in drug resistance in glioma and its association with FOXO1." (PMID 35141227, 2021). "Of notice, higher PID1 expression was positive associated with favorable prognosis of glioma patients." (PMID 27096627, 2016). "Besides, PID1 could correlate with efficacy of chemotherapeutic agents in glioma, suggesting that PID1 could be implicated in modulation of various biological processes." (PMID 37117198, 2023). "Initially, RT-qPCR results indicated lower PID1 expression in clinical glioma tissues relative to normal brain tissues." (PMID 35141227, 2021). "IGF2BP2 and DANCR were highly expressed in glioma cells and tissues, whereas PID1 and FOXO1 were poorly expressed." (PMID 35141227, 2021). "In the presence of FOXO1, glioma cell proliferation is inhibited, but addition of PID1 allows the proliferation ability to return to control levels." (PMID 35141227, 2021). "FOXO1 upregulates the expression of the protein phosphotyrosine interaction domain containing 1 (PID1), thereby inhibiting the tumorigenicity and growth of glioma stem cells." (PMID 35141227, 2021). "Our work here shows that PID1 augments the apoptotic effect of etoposide and cisplatin in medulloblastoma and glioma cell lines and that PID1 is required for part of the cisplatin-induced apoptosis of medulloblastoma cells." (PMID 28400607, 2017). "This suggests that cisplatin-induced apoptosis and mitochondrial depolarization in medulloblastoma and glioma cells occur, at least partially, via a mechanism that requires PID1." (PMID 28400607, 2017). "In this respect, it will be interesting to examine if PID1 augments and/or mediates response of medulloblastoma and glioma cells to irradiation and/or temozolomide, which are used in therapy of these tumors." (PMID 28400607, 2017). "We previously showed that higher tumor PID1 mRNA correlates with longer overall survival in glioma and medulloblastoma patients." (PMID 28400607, 2017). "Bortezomib mitigated the cisplatin-induced decrease of PID1 protein in a dose-dependent manner in both glioma (LN229, U87) and medulloblastoma (UW228) cells." (PMID 28400607, 2017). "Additionally, a large number of RNAs, such as PID1, a growth-inhibitory gene in embryonal brain tumors and gliomas, were found to interact with mRNAs." (PMID 37851698, 2023). "In a word, FOXO1 bound to PID1 promoter, promoting transcription of PID1 in glioma." (PMID 35141227, 2021). "Besides, higher PID1 mRNA levels also correlated with longer overall survival in patients with glioma, whereas in cell culture, overexpression of PID1 inhibited colony formation and induced mitochondrial depolarization, as sign of oxidative stress." (PMID 35141227, 2021). "In this study, we attempted to identify the interaction between FOXO1 and PID1 in glioma." (PMID 35141227, 2021). "Thus, PID1 sensitizes medulloblastomas and gliomas to etoposide and cisplatin, and mediates at least part of the chemotherapy response." (PMID 28400607, 2017). "PID1 tumor mRNA levels are highly correlated with longer survival in medulloblastoma and glioma patients, suggesting their tumors may have been more sensitive to therapy." (PMID 28400607, 2017). "Thus, PID1 sensitizes glioma and medulloblastoma cell lines to etoposide and cisplatin in a mechanism that involves NFκB." (PMID 28400607, 2017). "Furthermore, cell culture experiments in medulloblastomas and gliomas revealed that cisplatin, etoposide, and vincristine induced transcriptional upregulation of PID1." (PMID 27096627, 2016). "We therefore hypothesized that PID1 may sensitize gliomas and medulloblastoma cells to therapy." (PMID 28400607, 2017).
glioma (continued). "The longer survival of patients whose medulloblastoma and glioma tumors at diagnosis contained higher PID1 mRNA7 suggested that these patients’ tumors may be more responsive to therapy and raised the possibility that PID1 may sensitize medulloblastomas and gliomas to chemotherapy." (PMID 28400607, 2017). "IGF2BP2 also inhibits the phosphotyrosine interaction domain containing 1 (PID1) expression through the DANCR/FOXO1 axis, leading to drug resistance in glioblastoma cells and promoting glioma progression." (PMID 35625706, 2022). "Collectively, IGF2BP2 inhibits PID1 expression through the DANCR/FOXO1 axis, inducing drug resistance in GBM cells, and promoting glioma progression." (PMID 35141227, 2021). "FOXO1 binds and transcriptionally activates Phosphotyrosine Interaction Domain Containing 1 (PID1) and Migration and Invasion Inhibitory Protein (MIIP), that induce apoptosis and inhibit glioma growth and invasion." (PMID 31450858, 2019). "In the GAS5/miR-196a-5p/FOXO1/PID1 (MIIP) pathway of glioma stem cells, FOXO1 promotes GAS5 transcription and forms a positive feedback loop that regulates the biological behavior of glioma stem cells." (PMID 30736838, 2019). "In our cultured medulloblastoma (UW228), glioma (LN229) and neuroblastoma (CHLA-255) cell lines the etoposide- and cisplatin-induced increase in PID1 mRNA was blocked by NFκB inhibitors, suggesting that it was mediated by NFκB." (PMID 28400607, 2017). "Moreover, the GAS5/miR-196 axis increases the level of phosphotyrosine interaction domain containing 1 (PID1) protein, thus inhibiting glioma stem cell tumorigenicity and growth." (PMID 39941145, 2025). "FOXO1 promoted expression of PID1, and the binding of FOXO1 to the PID1 promoter could activate the transcription of PID1 in glioma stem cell." (PMID 35141227, 2021).
Obesity (9 papers, 2010 to 2025). Accumulation of substantial excess body fat. "PID1 has previously been associated with factors such as obesity and Type 2 diabetes." (PMID 39482899, 2025). "Many studies have indicated that PID1 may play an important role in the development of obesity-related IR." (PMID 30990811, 2019). "Many studies have demonstrated increased expression of PID1 in adipose tissues in obesity." (PMID 30990811, 2019). "Studies examining PID1 has been mostly in the context of obesity and insulin resistance." (PMID 27656889, 2016). "Amino acid sequence analysis revealed that PID1 has a phosphotyrosine-binding (PTB) domain, which can bind to phosphorylated tyrosine residues, impair insulin signal transduction, and lead to obesity-related IR." (PMID 30990811, 2019). "A recent study has suggested that adipose tissues rather than adipocytes in obesity subjects were unable to respond to insulin, which partly explained for differential roles of PID1." (PMID 37117198, 2023).
Insulin resistance (5 papers, 2012 to 2023). Increased resistance towards insulin, that is, diminished effectiveness of insulin in reducing blood glucose levels. "Although PID1 was reported to induce insulin resistance in the transgenic mice, hepatoma cells with PID1 overexpression still retained the capacity to respond to insulin in our study." (PMID 37117198, 2023).
glioblastoma (3 papers, 2017 to 2022). The most malignant astrocytic tumor (WHO grade IV). "We found that PID1 increased the apoptosis induced by cisplatin and etoposide in medulloblastoma and glioblastoma cell lines." (PMID 28400607, 2017). "Taken together, our results demonstrate for the first time that PID1 increases apoptotic response of glioblastoma and medulloblastoma cell lines to cisplatin and etoposide and that PID1 is required for cisplatin-mediated apoptosis." (PMID 28400607, 2017). "Phosphotyrosine Interaction Domain containing 1 (PID1; NYGGF4) inhibits growth of medulloblastoma, glioblastoma and atypical teratoid rhabdoid tumor cell lines." (PMID 28400607, 2017).
Hyperglycemia (3 papers, 2018 to 2024). An increased concentration of glucose in the blood. "Our GSEA enrichment analysis results indicate that PID1 may be associated with metabolic pathways, particularly in galactose and glucose metabolism, suggests that targeting these processes may alleviate hyperglycemia-related complications, ultimately benefiting patient outcomes." (PMID 39763654, 2024). "In addition, under diabetogenic conditions, Pid1 inactivation has been shown to improve hyperinsulinemia and hyperglycaemia by stimulating glucose uptake in the muscle and adipose tissue of Pid1-/- mice." (PMID 32653024, 2020).
brain tumor (2 papers, 2017 to 2023). "We tested the hypothesis that PID1 enhances chemotherapy-induced cell death in brain tumor cell lines." (PMID 28400607, 2017). "Thus, chemotherapy can increase PID1 mRNA in brain tumor cell lines." (PMID 28400607, 2017). "We hypothesized that PID1 sensitizes brain tumors to therapy." (PMID 28400607, 2017). "Thus PID1 augmented the apoptotic effect of cisplatin and etoposide in medulloblastoma and GBM cell lines, suggesting sensitization of brain tumor cell lines to chemotherapy by PID1." (PMID 28400607, 2017).
hepatocellular carcinoma (2 papers, 2018 to 2023). A malignant tumor that arises from hepatocytes. "Overall, we describe a PID1-mediated, dynamics-driven mechanism that can regulate apoptosis induced by diverse anticancer agents in hepatoma cells." (PMID 37117198, 2023). "Hepatoma cells with high PID1 levels were more resistant to oxidative stress, and significantly higher percentage of apoptosis was detected in HepG2 and Hepa1–6 cells." (PMID 37117198, 2023). "We initially assessed the PID1 levels in three human hepatoma cell lines (HepG2, Hep3B and SK-Hep-1) and two mice hepatoma cell lines (Hepa1–6 and H22)." (PMID 37117198, 2023). "In line with this, we observed partial co-localization with the lysosomal marker LAMP1 in PID1-knockdown hepatoma cells." (PMID 30100244, 2018). "We performed PID1 overexpression in hepatoma cells with low PID1 expression levels." (PMID 37117198, 2023). "Hence, these results indicated that PID1 could accelerate Sorafenib-induced Raf-1 activation and facilitate the formation of Raf-1/BRAF heterodimerization, thereby blocking AKT activation via Raf-1-dependent pathway and leading to increased sensitivity of hepatoma cells to Sorafenib." (PMID 37117198, 2023).
medulloblastoma (2 papers, 2016 to 2017). A malignant, invasive embryonal neoplasm arising from the cerebellum. "Clinically, levels of PID1 mRNA in medulloblastoma and glioma tumors directly correlate with patient survival." (PMID 28400607, 2017). "JSH-23 also diminished baseline and etoposide-induced increase in PID1 mRNA in LN229 GBM cells and suppressed the cisplatin-induced increase in PID1 mRNA in UW228 medulloblastoma cells." (PMID 28400607, 2017). "We examined effect of cisplatin, etoposide, and vincristine on PID1 mRNA level in UW228 and D283MED medulloblastoma cell lines and LN229, U87, LN18, and D54 GBM cell lines." (PMID 28400607, 2017). "Taken together, these data suggest that the etoposide- and cisplatin-induced increase in PID1 mRNA in LN229 GBM and UW228 medulloblastoma cells is at least partly mediated by NFκB." (PMID 28400607, 2017).
Sepsis (2 papers, 2023 to 2024). Sepsis is defined as life-threatening organ dysfunction caused by a dysregulated host response to infection. "Importantly, we identified six critical genes, including CS, CYP1B1, FLVCR1, IFIT2, MAPK14, and PID1, which showed favorable diagnostic value in screening sepsis samples from normal samples." (PMID 37398680, 2023). "A predictive model for sepsis was created using three crucial genes—CX3CR1, PID1, and PTGDS—to enhance diagnostic precision." (PMID 39763654, 2024). "This study identified three molecular signatures (CX3CR1, PID1 and PTGDS) linked to the diagnosis and poor prognosis of sepsis and ARDS, validated by RT-qPCR and H&E staining in both patient and mouse samples." (PMID 39763654, 2024). "For sepsis, CX3CR1, PID1 and PTGDS are strongly associated with immune pathways such as “Allograft rejection” and “Asthma”." (PMID 39763654, 2024). "We found that the expression of MAPK14 and CYP1B1 was distinctly increased in sepsis samples compared with normal samples, while the expression of PID1, CS, FLVCR1, and IFIT2 was distinctly decreased in sepsis samples compared with normal samples." (PMID 37398680, 2023). "This is consistent with previous studies in which PID1 was able to serve as a biomarker for the assessment of immune status in sepsis and could serve as stratification tools prior to immunostimulatory treatment and to monitor drug efficacy." (PMID 37398680, 2023). "Combining the findings from both algorithms and WGCNA, three shared biomarkers (CX3CR1, PID1 and PTGDS) were discovered for both the sepsis and ARDS groups." (PMID 39763654, 2024). "We categorized the sepsis dataset by patient survival outcomes and examined the mRNA expression levels of the genes CX3CR1, PID1, and PTGDS." (PMID 39763654, 2024). "This research is unique due to the combination of various machine learning techniques, which systematically identifying three hub genes (CX3CR1, PID1 and PTGDS) as possible biomarkers for diagnosing and predicting outcomes in sepsis and ARDS." (PMID 39763654, 2024). "In this study, differential gene analysis, WGCNA, and machine learning were utilized to identify novel gene signatures related to sepsis and ARDS (CX3CR1, PID1, and PTGDS)." (PMID 39763654, 2024). "Using bioinformatics techniques, we identified PID1, CS, CYP1B1, FLVCR1, IFIT2, and MAPK14 as six MRGs that are essential in the course of sepsis." (PMID 37398680, 2023). "PID1 acts as an indicator for assessing immunomodulatory treatment in sepsis and can function as a stratification tool to monitor the effectiveness of IFN-γ therapy prior to immunostimulatory intervention in sepsis." (PMID 39763654, 2024). "Finally, we collected 15 sepsis samples and 15 normal samples and performed RT-PCR to examine the expression of CS, CYP1B1, FLVCR1, IFIT2, MAPK14, and PID1 in our cohort, which further confirmed our previous findings." (PMID 37398680, 2023).
amebiasis (1 paper, 2022). A parasitic infectious disorder caused by amoebas. "However, some factors thought to be important for dcMO development (i.e., Flt3, Pou2f2, Pid1, and Hpgd) were strongly downregulated while their expression by monocytes from the amebiasis model was comparably higher." (PMID 36010615, 2022).
asthma (1 paper, 2024). "Furthermore, changes in PID1 are linked to reduced lung performance and heightened asthma." (PMID 39763654, 2024).
chronic obstructive pulmonary disease (1 paper, 2020). A chronic and progressive lung disorder characterized by the loss of elasticity of the bronchial tree and the air sacs, destruction of the air sacs wall, thickening of the bronchial wall, and mucous accumulation in the bronchial tree. "Other identified genes previously reported in GWAS to be associated with CVD-related traits were ELL2 (GWAS of BP, insulin and glucose), TRPS1 (GWAS of BP), PID1 (GWAS of stroke, lung function and chronic obstructive pulmonary disease) and WIPF1 (GWAS of resting heart rate)." (PMID 31999706, 2020).
COVID-19 (1 paper, 2022). A disease caused by infection with severe acute respiratory syndrome coronavirus 2. "In addition, some mito-DEGs were reversely altered in the AT2 and AT1 subsets (e.g., LRRK2, PID1, SOD2, CLIC4, and ERBB4) or showed altered expression in the AT2 or AT1 subset in patients with COVID-19 (–D)." (PMID 35844544, 2022).
cystitis (1 paper, 2014). Inflammation of the urinary bladder. "A third group was comprised of 6 ASB isolates that displayed a high analgesic phenotype, relative to PID1, attenuating cystitis allodynia from 75% to 85% (grey bars)." (PMID 25405579, 2014).
diabetes (1 paper, 2024). "Interestingly, several DEGs identified in this study had been reported to be associated with the occurrence and progression of diabetes, including SERPINF1, PID1, IL1R1 and PGC." (PMID 39845878, 2024).
ectodermal dysplasia (1 paper, 2022). "Notably, during the initial WGS analysis of this patient, who also presented a phenotype of recurrent infections, genes related to ectodermal dysplasia were included in addition to the PID-1 gene panel." (PMID 35874679, 2022).
endometriosis (1 paper, 2024). The growth of functional endometrial tissue in anatomic sites outside the uterine body. "Pid1, Saa3, Apoe, and Lrp1 were key DEGs in the monocyte-derived LpM population, and qPCR analysis also confirmed an upregulation of these genes in Tim4− peritoneal macrophages isolated from mice with induced endometriosis compared to those without (Saa3, Lrp1,P < 0.01)." (PMID 39255000, 2024).
ischemia (1 paper, 2016). A hypoperfusion of the BLOOD through an organ or tissue caused by a PATHOLOGIC CONSTRICTION or obstruction of its BLOOD VESSELS, or an absence of BLOOD CIRCULATION. "Overexpression of PID1 in human myoblasts results in reduced insulin signaling which has been pointed out as a neuroprotective agent acting mainly against apoptosis, beta amyloid toxicity, oxidative stress, and ischemia." (PMID 27656889, 2016).
thyroid cancer (1 paper, 2020). "PID1, a gene that regulates the sensitivity of fat and muscle cells to insulin signals, has been reported as a feature gene in several cancers, including thyroid cancer." (PMID 32299435, 2020).
cancer (6 papers, 2017 to 2024). A tumor composed of atypical neoplastic, often pleomorphic cells that invade other tissues. "The role of PID1 (Phosphotyrosine interaction domain-containing protein 1) in cancer involves modulating lipid metabolism and mitochondrial function, indicating its potential impact on tumor metabolic reprogramming and its association with cancer progression." (PMID 38962012, 2024). "PID1 was recently identified as one of the two signature genes (the other gene is SPTBN2) in seven cancers." (PMID 35886011, 2022). "In conclusion, this study elucidates a mechanism by which IGF2BP2 promotes DANCR expression and stability through FOXO1 ubiquitination-mediated PID1 expression, thereby promoting cancer cell survival and tumor growth as well as promoting the resistance of GBM cells to etoposide." (PMID 35141227, 2021). "This suggests that the direct correlation between higher PID1 mRNA levels and longer patient survival may reflect a PID1-mediated relative sensitivity of these cancers to therapy." (PMID 28400607, 2017).
tumor (5 papers, 2017 to 2024). "It was observed that PID1 deficiency evidently decreased tumor growth in Doxorubicin-treated nude mice but restrained the anti-tumor potential of Sorafenib." (PMID 37117198, 2023). "In the current experiments, we set about to examine the regulatory effects that IGF2BP2 on GBM cell chemoresistance and analyze the potential regulatory network of the IGF2BP2/DANCR/FOXO1/PID1, aiming to provide a novel antitumor target for tumor treatment." (PMID 35141227, 2021). "GAS5 also inhibited tumor inducer miR-196-5p, which led to suppressed tumor growth by positive regulation of tumor suppressors forkhead box protein O1 (FOXO1) and phosphotyrosine interaction domain containing 1 (PID1)." (PMID 34322395, 2021).
neurodegenerative disease (1 paper, 2016). A disorder of the central nervous system characterized by gradual and progressive loss of neural tissue and neurologic function. "These evidences suggest the involvement of PID1 gene in neuronal processes and neurodegenerative disease." (PMID 27656889, 2016).
PID1 also shares sentences with these, for which no sentence is quoted: Alzheimer disease (2 papers); atypical teratoid rhabdoid tumor (1); bacterial infection (1); cardiovascular disease (1); gestational hypertension (1); Hyperbilirubinemia (1); Hyperinsulinemia (1); hyperlipidemia (1); Hypertension (1); neuroblastoma (1); pneumonia (1); psoriasis (1); rhabdoid tumor (1); Stroke (1); tauopathies (1); Type 2 diabetes (1).